SNORA74 (Small nucleolar RNA SNORA74 )
Synonyms: LOC124906140
Gene: Small nucleolar RNA gene on chromosome 2 (65,158,662 to 65,158,860, forward strand). Ensembl gene ENSG00000272025.
Gene Ontology:
Biological process: RNA processing
Cellular component: nucleolus
Homologues: Orthologues: chimpanzee SNORA74 (97% identical), macaque SNORA74 (93% identical), rabbit SNORA74 (78% identical). Paralogues in human: SNORA74A (85% identical), SNORA74B (57% identical), SNORA74C-2 (57% identical), SNORA74C-1 (56% identical), SNORA74 (44% identical), SNORA74D (35% identical), SNORA74 (32% identical).